GFAP (glial fibrillary acidic protein)
Diseases named in the same sentence as GFAP in open-access papers (continued):
Sharing a sentence is not in itself a finding about the gene and the disease.
COVID-19 (continued). "In patients with severe COVID-19, increased levels of plasma biomarkers for CNS injury, including GFAP (astrocytic activation/injury) and NfL (axonal damage) are exhibited." (PMID 35572514, 2022). "In par with that, a recent study profiling brain tissue of patients with COVID-19 found microglial activation and increased tissue GFAP levels." (PMID 35937088, 2022). "SARS-CoV2 infection was reported to lead to elevated plasma levels of neurofilament light chain protein (NfL) and glial fibrillary acidic protein (GFAP) two markers usually indicative of CNS injury in patients with COVID-19." (PMID 33953960, 2021). "A rise in the glial fibrillary acidic protein (GFAP), commonly regarded as a marker of astrocyte reactivity, was found in the white matter of a COVID-19 patient with encephalomyelitis-like brain damage." (PMID 34912192, 2021). "The expressions of Iba1 and GFAP throughout the retina in COVID-19 and control post-mortem samples were determined." (PMID 34829775, 2021). "Plasma levels of GFAP were elevated in moderate/severe stages of COVID-19 suggesting that astrogliosis is an early CNS response to SARS-CoV-2 infection." (PMID 34912192, 2021). "GFAP was increased in both severe and moderate COVID-19 cases, whereas NfL was increased only in severe cases compared to control." (PMID 33115334, 2021). "It is important to note that our putative biomarkers of disease progression in COVID-19 (IL6, CKAP4, Gal-9, IL-1ra, LILRB4 and PD-L1) were associated to NfL but to a much lesser extent to GFAP and tau." (PMID 33737684, 2021). "A longitudinal study showed that elevated NfL and GFAP concentrations normalized at 6-month follow-up, regardless of prior disease severity or persisting neurological symptoms, in all COVID-19 patients." (PMID 34593760, 2021). "Correlation analysis identified SCARB2 is most correlated with tau and GFAP, and EDA2R is most correlated with Nfl, suggesting that these novel proteins are associated with COVID-19-related early or later CNS injury, respectively." (PMID 33737684, 2021). "Plasma samples from 57 subjects at < 48 h of COVID-19 hospitalization, and 20 matched controls were interrogated for the levels of six BIMs—including GFAP, S100B, Syndecan-1, UCHLI, MAP2 and NSE, two EIMs—including sICAM1 and sVCAM1." (PMID 34838058, 2021). "Analysis of markers indicating CNS lesions revealed elevated levels of neurofilament light chain (NfL) and glial fibrillary acidic protein (GFAP) in plasma of patients with moderate to severe COVID-19." (PMID 34942956, 2021). "Specifically, astrocytic injury was observed in the acute phase of COVID-19, as shown by high plasma levels of glial fibrillary acidic protein (GFAP), with more pronounced findings in hospitalized patients." (PMID 35002631, 2021). "Patients with severe COVID-19 had significantly higher concentrations of GFAP and NfL in plasma than controls, and GFAP was also increased in patients with moderate COVID-19." (PMID 33304309, 2020). "For example, plasma concentration of the astrogliosis marker GFAP in patients with moderate to severe COVID-19 is significantly increased." (PMID 33304243, 2020). "The generalised increase in GFAP expression was found in the white matter of a COVID-19 victim with disseminated encephalomyelitis." (PMID 33304243, 2020). "Moreover, in people who had acute brain dysfunction (eg, encephalopathy, stroke, encephalitis), NfL, GFAP, and tau were elevated in serum even several months following COVID-19." (PMID 41020593, 2025). "Molecular analyses have revealed the presence of SARS-CoV-2 proteins and injury markers, such as glial fibrillary acidic protein (GFAP) and agrin, in astrocyte- and neuron-derived exosomes (ADEVs and NDEVs), even in individuals with mild acute COVID-19, indicating persistent cellular dysfunction." (PMID 40507911, 2025).
COVID-19 (continued). "Although MRI-negative myelitis can be observed in myelin oligodendrocyte glycoprotein antibody-associated disease (MOGAD), lupus myelitis, and glial fibrillary acidic protein (GFAP) astrocytopathy, post-COVID-19 myelitis lacks specific biomarkers, complicating both diagnosis and treatment." (PMID 41451231, 2025). "After adjusting for age, COVID-19 patients with delirium had significantly higher GFAP levels at day 3 [270.5 (148.0,375.0) pg/ml vs. 113.0 (70.9,196.0) pg/ml, p = 0.021] and higher MMP-9 levels [50.3 (43.1,13.2) μg/ml vs. 28.9 (17.9,47.9) μg/ml, p = 0.003] at hospital discharge." (PMID 39352661, 2025). "High levels of biomarkers for CNS lesions, such as glial fibrillary acid protein (GFAP) and neurofilament light chain protein (NfL), were found in the cerebrospinal fluid of severe and moderate cases of COVID-19, suggesting that the astrocytes of these patients were in an active state." (PMID 41139159, 2025). "GFAP was increased in acute and mild–moderate COVID-19 individuals who recovered after infection." (PMID 41369364, 2025). "It is worth noting that discrepancies exist regarding S100B and GFAP expression in acute COVID-19." (PMID 39451987, 2024). "Furthermore, both SARS-CoV-2 and elevated GFAP were reportedly detectable in the CSF of a COVID-19 patient nearly three weeks after symptom onset and after having tested negative twice for the virus." (PMID 39451987, 2024). "COVID-19 severity and mortality have been correlated with increased NfL and GFAP levels." (PMID 38438479, 2024). "As far as we know, this is the first study to describe, simultaneously, the multisystemic and multiple biochemical parameters between survival and not survival severe COVID-19 patients associated to nervous system biomarkers NfL, GFAP, UCH-L1, and TAU." (PMID 37996731, 2024). "As for brain injury, by monitoring the serum markers of brain injury (NfL) and neuro-collagen fibrillary acidic protein (GFAP) in patients, researchers have found that brain injury is a common consequence of both COVID-19 and common influenza, and therefore lacks specificity." (PMID 38311757, 2024). "Furthermore, additional studies in the literature support the relation between GFAP levels and the development of severe disease in COVID-19 patients." (PMID 39772122, 2024). "The levels of serum neurofilament light chain (sNfl) and glial fibrillary acidic protein (GFAp) may serve as prognostic indicators for in-hospital mortality related to COVID-19." (PMID 38793545, 2024). "In a different study, higher levels of the serum neuronal injury marker Ubiquitin carboxy-terminal hydrolase L1 (UCHL1), but not GFAP, were linked to neurological manifestations in COVID-19 patients at ICU admission." (PMID 39451987, 2024). "In a comparative analysis between subjects with severe COVID-19 and those with mild long COVID-19 (characterized by persistent headache for more than 12 weeks after initial serological sampling), serum GFAP levels were significantly higher in the former cohort." (PMID 39451987, 2024). "Studies on COVID-19 patients have highlighted critical brain injury biomarkers, such as neurofilament light chain (NfL), glial fibrillary acidic protein (GFAP), and matrix metalloproteinase-9 (MMP-9), which are essential in understanding the extent of neural damage." (PMID 39064167, 2024). "NfL and GFAP were selected in this study due to the reported elevation in acute COVID-19." (PMID 38438479, 2024). "In addition, immunostaining detected marked GFAP-positive hyperplasia of astrocytes in COVID-19 brains, implying their extensive activation and possible participation in brain injury." (PMID 36609561, 2023). "An early study demonstrated that after a short follow-up of 11.4 days, patients with severe COVID-19 displayed a decrease in the earliest plasma GFAP peak, whilst NfL showed a sustained increase, perhaps reflecting a sequence of early astrocytic response and more delayed axonal injury." (PMID 36769057, 2023).
COVID-19 (continued). "However, some studies have reported contradictory findings, which warrant a comprehensive analysis of the relationship between neurological biomarkers (GFAP and NfL) and COVID-19." (PMID 37958721, 2023). "However, in this meta-analysis, we observed a significant difference in the overall pooled GFAP level in patients with moderate and severe COVID-19 when compared to the healthy controls." (PMID 37958721, 2023). "Furthermore, five studies were included in the meta-analysis of pooled GFAP levels between moderate and severe COVID-19 and healthy controls." (PMID 37958721, 2023). "Exploring the relationship between neurological biomarkers (GFAP and NfL) and COVID-19 could be of great clinical value." (PMID 37958721, 2023). "Taken together, previous studies have reported changes in NfL and GFAP levels in COVID-19 patients." (PMID 37958721, 2023). "However, at late timepoints (>6 weeks) elevations of NfL and GFAP were only seen in participants who had sustained a neurological complication of COVID-19 in the acute phase of their illness." (PMID 38135686, 2023). "Likewise, in the acute phase of COVID-19, it has been shown that increased levels of glial fibrillary acidic protein (GFAP) correlate with COVID-19 severity." (PMID 37759493, 2023). "Similarly, increased levels of some biomarkers associated with CNS damage, such as the S100 B protein (protein calcium-binding B) and fibroglial acid protein (GFAP) have been observed during these post-COVID-19 neuropsychiatric manifestations." (PMID 37754054, 2023). "In COVID-19 patients, a correlation was found between the levels of neuroaxonal damage biomarkers, NfL and T-tau (r = 0.583; p < 0.001), but also between NfL and GFAP (r = 0.671; p < 0.001) and between T-tau and GFAP (r = 0.667; p < 0.001)." (PMID 36769057, 2023). "Thus, early studies demonstrated that patients with severe COVID-19 had higher plasma concentrations of GFAP and NfL than controls, while GFAP was also increased in patients with a moderate manifestation of the disease." (PMID 36769057, 2023). "To clarify the role of NfL, GFAP and sCD163 as a sign for CNS damage presenting with NS, we stratified hospitalized COVID-19 patients according to the severe presence of NS during the acute stage of COVID-19 and self-referred NS three months after hospital discharge." (PMID 37759493, 2023). "Interestingly, we found that compared to control, both ARDS and COVID-19 exhibited increased numbers of GFAP+ astrocytes, defined as GFAP+ somata, per unit area in all ION regions." (PMID 37483351, 2023). "Plasma levels of both GFAP and neurofilament light chain protein (NfL), a biomarker predictive of intra-axonal neuronal injury, were measured in 47 patients with mild, moderate, or severe COVID-19 and matched controls." (PMID 35922744, 2023). "High plasma and CSF levels of NfL and GFAP in COVID-19 could be due to a proinflammatory systemic and brain response that involves microglial activation and subsequent neuronal damage." (PMID 37759493, 2023). "The finding of neurofilaments light chain protein (NfL), an expression of axonal damage, and of glial fibrillary acidic protein (GFAp), an expression of astrocytic activation/injury, in the plasma of COVID-19 patients demonstrates the damage induced by the virus on the nervous system." (PMID 35632776, 2022). "In addition, the serum levels of total tau, phosphorylated tau-181, GFAP and NfL chain were significantly elevated in individuals that died in the hospital due to COVID-19." (PMID 36298824, 2022). "A study demonstrated that biomarkers for neurodegeneration such as neurofilament light chain protein (NFL), tau proteins, and glial fibrillary acidic protein (GFAP) are increased in the cerebrospinal fluid of COVID-19 patients by 63%, 37%, and 16%, respectively." (PMID 36277564, 2022).
COVID-19 (continued). "Immunofluorescence staining of 200–250 μm free-floating sections further confirmed the results of the conventional immunohistochemical staining revealing a much larger number of astrocytes with intense GFAP labeling in old COVID-19 patients compared to young COVID-19 patients." (PMID 35785352, 2022). "In COVID-19 patients with altered NfL and GFAP, values of these markers had normalized in all individuals at 6-month follow-up, suggesting that post-COVID-19 neurological sequelae may be not accompanied by ongoing brain injury." (PMID 35572561, 2022). "Recent studies have found elevated levels of GFAP in serum and/or plasma of COVID-19 patients." (PMID 36268187, 2022). "Age is a major factor affecting disease severity and outcome of COVID-19 patients (also see a previous work, an observation which may require the development of age-adjusted norms for biomarkers such as GFAP and UCH-L1314)." (PMID 33115334, 2021). "Therefore, this systematic review and meta-analysis aimed to determine the pooled SMD of GFAP and NfL between COVID-19 patients and healthy controls and to generate evidence for the association between neurological injury-related biomarkers and the severity of COVID-19 infection." (PMID 37958721, 2023). "Therefore, this systematic review and meta-analysis aimed to determine the pooled standardized mean differences (SMD) of GFAP and NfL between COVID-19 patients and healthy controls, generating evidence for the association between neurological injury-related biomarkers and COVID-19 prognosis." (PMID 37958721, 2023). "Additionally, the pooled GFAP and NfL levels were significantly lower in patients with mild COVID-19 compared to severe cases, while the pooled level of GFAP and NfL were significantly increased in patients with moderate and severe COVID-19 when compared to the healthy controls." (PMID 37958721, 2023). "Moreover, the levels of specific peripheral biomarkers that are routinely used in clinical practice for AD diagnosis—such as total tau protein in association with IL-6, Neurofilament Light Chain (NFL) and Glial Fibrillary Acidic Protein (GFAP)—are elevated in the CSF and serum of COVID-19 patients." (PMID 37998336, 2023). "Interestingly, severe COVID-19 patients show a decrease in GFAP levels between initial (a mean of 13 days after onset of symptoms) and follow-up tests (a mean of 11.4 days after initial test), yet an increase in NfL, suggesting initial astrocyte activation followed by delayed neuronal injury." (PMID 35572514, 2022). "Furthermore, we aimed to explore whether testosterone levels are associated with GFAP and UCH-L1, showing biomarkers of neurological disorders in male patients with a severe form of COVID-19." (PMID 36363686, 2022). "Therefore, we aimed to explore whether testosterone levels are associated with glial fibrillary acidic protein (GFAP) and ubiquitin carboxy-terminal hydrolase L1 (UCH-L1), biomarkers of brain injury, in patients with a severe form of COVID-19." (PMID 36363686, 2022). "However, increased levels of GFAP have been detected in the plasma of COVID-19 patients." (PMID 34769052, 2021). "Supporting our findings, the CSF analysis of a patient from Sweden with COVID-19-related acute necrotizing encephalopathy, showed only a slight increase in protein and monocytes, while the levels of neuronal injury markers such as tau, NfL (neurofilament light), and GFAP were extremely high." (PMID 33297938, 2020). "In the presence of delirium, we found elevation of age-corrected blood-levels of GFAP and MMP-9, specifically in COVID-19 patients." (PMID 39352661, 2025). "In severe COVID-19 patients, UCHL1, along with other neurological biomarkers, such as GFAP, NfL, and TAU, can serve as an early predictor of poor prognosis." (PMID 39201608, 2024). "First, we compared the plasma levels of NfL, GFAP, TAU, and UCH-L1 among severe and mild COVID-19 patients and health age-matched controls." (PMID 37996731, 2024).
COVID-19 (continued). "Phenotypically, hypertrophic astrocytes with lower branching complexity and co-expression of GFAP/collagen IV and aquaporin 4 (AQP4) were observed in COVID-19 patients." (PMID 39451987, 2024). "Upregulation of astrocyte gene expression in glial fibrillary acidic protein (GFAP), thrombospondin 2 (Thbs2), leukemia inhibitory factor (Lif), and interleukin 6 (IL-6) by physical activity deserve further studies to explore whether it helps in immune responses, such as those against COVID-19." (PMID 39409085, 2024). "Concomitantly, GFAP and UCH-L1 levels were found significantly higher among deceased patients, when compared to severe survival COVID-19 patients." (PMID 37996731, 2024). "In our study, it was possible to observe that all investigated plasma biomarkers (GFAP, NfL, TAU, UCH-L1) presented significantly higher levels among severe COVID-19 when compared to health controls (p < 0.01)." (PMID 37996731, 2024). "Some common biomarkers that can be considered for neuronal injury during COVID-19 and AD include p-tau, neurofilament light chain protein (NFL), and glial fibrillary acidic protein (GFAp) microvascular injury." (PMID 38535583, 2024). "First, we quantified the number of Glial fibrillary acidic protein (GFAP) positive astrocytes in the ION in controls, ARDS, and COVID-19." (PMID 37483351, 2023). "Overall, we found two novel FTD-COVID-19 comorbid genes, GFAP and RTN4, and five novel FTD-Breast cancer comorbid genes, AKT3, GFAP, ADCYAP1R1, VDAC1, and C4A, in this study." (PMID 37834358, 2023). "Our results showed that the genes AKT3, GFAP, ADCYAP1R1, VDAC1, and C4A have significant transcriptomic alterations in FTD along with the comorbidity status with COVID-19 and breast cancer." (PMID 37834358, 2023). "This meta-analysis assessed the relationship between glial fibrillary acidic protein (GFAP) and neurofilament light chain (NfL) levels in the blood and neurological injury in COVID-19 patients." (PMID 37958721, 2023). "Results from the DPI analysis showed that the genes GFAP and RTN4 were found to be involved in COVID-19 with a score of 0.885 and 0.692." (PMID 37834358, 2023). "A handful of studies have explored the measurement of biomarkers NfL, GFAP, tau proteins, IL-6, IL-10, TNF-α, and CPR during acute COVID-19 and PASC." (PMID 37545721, 2023). "Moreover, compared to the control group, AD and COVID-19 were associated with a significantly reduced percentage of cluster 3 characterized by neural cell adhesion molecule 1 (NCAM1), neural cell adhesion molecule 2 (NCAM2), and glial fibrillary acidic protein (GFAP)." (PMID 36211330, 2022). "In the present study, therefore, we aimed to explore the dynamic of GFAP and UCH-L1 during the ICU stay of patients with severe COVID-19." (PMID 36363686, 2022). "Recent studies have shown increased levels of neuroinflammatory proteins and neural injury markers such as glial fibrillary acidic protein (GFAP), neurofilament light chain (NFL), and Tau in patients with COVID-19 in plasma or cerebrospinal fluid (CSF)." (PMID 35937088, 2022). "Two plasma biomarkers of CNS injury, neurofilament light-chain protein (NfL, a marker of neuroaxonal injury) and glial fibrillary acidic protein (GFAP, a marker of astrocytic activation/injury), were increased in severe COVID-19 patients." (PMID 34593760, 2021). "Another study showed elevated plasma levels of neurofilament light chain protein (NfL), a marker of neuronal injury and glial fibrillary acidic protein (GFAP), a marker of astroglial injury in COVID-19 patients, suggestive of direct CNS damage." (PMID 34646224, 2021). "To investigate the effects of COVID-19 on BIMs, we examined systemic levels of six previously validated BIMs—MAP2, NSE, GFAP, S100B, Syndecan-1 and UCHL1." (PMID 34838058, 2021). "When compared to never-COVID-19 controls, we also found statistically significant reductions in the GFAP (β = −0.091, P = 0.007) and NfL (β = −0.077, P = 0.022) among those with N-PASC." (PMID 41494242, 2026).